PAG1 (phosphoprotein membrane anchor with glycosphingolipid microdomains 1)
Description:
Negatively regulates TCR (T-cell antigen receptor)-mediated signaling in T-cells and FCER1 (high affinity immunoglobulin epsilon receptor)-mediated signaling in mast cells. Promotes CSK activation and recruitment to lipid rafts, which results in LCK inhibition. Inhibits immunological synapse formation by preventing dynamic arrangement of lipid raft proteins. May be involved in cell adhesion signaling.
Synonyms: CBP; PAG
Tractability: Antibody: UniProt places it where antibodies can reach, with high confidence; its Gene Ontology location is reachable by antibodies, with high confidence; UniProt predicts a signal peptide or a membrane-spanning region. PROTAC: ubiquitination databases record sites on it; its protein half-life has been measured.
Gene: Protein-coding gene on chromosome 8 (80,967,810 to 81,112,116, reverse strand). Ensembl gene ENSG00000076641.
Subcellular location: Cell membrane
Subcellular location (Human Protein Atlas): Plasma membrane; Vesicles
Pathways (Reactome):
Immune System: Phosphorylation of CD3 and TCR zeta chains
Signal Transduction: GAB1 signalosome
Gene Ontology:
Molecular function: protein binding; SH2 domain binding; signaling adaptor activity
Biological process: intracellular signal transduction; regulation of T cell activation; negative regulation of T cell activation; signal transduction
Cellular component: membrane raft; plasma membrane
Genetic constraint (gnomAD): Loss-of-function variants: 19 observed, 26.59 expected, observed/expected ratio (o/e) 0.71, 90% interval 0.5 to 1.05. The upper end of that interval is the gene's LOEUF score, 1.05, which puts it in group 4 of 6, group 1 being the genes least tolerant of losing a copy. Missense variants: 386 observed, 473.74 expected, observed/expected ratio (o/e) 0.81, 90% interval 0.75 to 0.89. Synonymous variants: 180 observed, 187.89 expected, observed/expected ratio (o/e) 0.96, 90% interval 0.85 to 1.08.
Homologues: Orthologues: chimpanzee PAG1 (99% identical), macaque PAG1 (96% identical), pig PAG1 (87% identical), dog PAG1 (85% identical), guinea pig PAG1 (84% identical), rabbit PAG1 (84% identical), rat Pag1 (80% identical), mouse Pag1 (79% identical), tropical clawed frog pag1 (50% identical), zebrafish pag1 (35% identical).
Diseases named in the same sentence as PAG1 in open-access papers:
PAG1 is named in the same sentence as 49 diseases in open-access papers, as found by Europe PMC text mining. Sharing a sentence is not in itself a finding about the gene and the disease. The quoted sentences say what the papers report.
asthma (4 papers, 2017 to 2024). "In summary, at least 49 genes (including PAG1) are likely targets of published asthma risk variants, most (90%) identified based on the LD between risk variants and eQTLs." (PMID 29333270, 2017). "Although there is limited existing literature connecting PAG1 to kidney disease, our findings demonstrated an upregulation of PAG1 in DN, aligning with its recognized pro-inflammatory role in conditions such as asthma and nasopharyngeal carcinoma." (PMID 37988198, 2023). "Evidence from GWAS suggested that PAG1 was related to risk of allergic and inflammatory diseases, such as asthma, although there was no direct proof of an association with AD." (PMID 38259487, 2023). "We recently used such approaches to identify PAG1 as a likely target gene of the asthma risk variants located on chromosome 8q2170, for which no eQTL support was available at the strict significance threshold used above." (PMID 29333270, 2017). "Similarly, we have recently been interested in understanding how variation in PAG1 expression might contribute to asthma pathophysiology." (PMID 29333270, 2017).
nasopharyngeal carcinoma (3 papers, 2023 to 2025). A carcinoma arising from the nasopharyngeal epithelium. "Functional studies reveal that PAG1 depletion impairs the proliferative capacity, migratory potential and invasive properties of nasopharyngeal carcinoma cells." (PMID 40282426, 2025). "PAG1 has been proved to be essential for the development of various kinds of malignancies, including Laryngeal carcinoma and nasopharyngeal carcinoma." (PMID 36920166, 2023).
Colon cancer (2 papers, 2016 to 2023). "Colon cancer and melanoma tumors are more susceptible to PD-1 inhibition when PAG1 is deleted." (PMID 37589508, 2023). "Overexpression of PAG1 has also been shown to inhibit the growth of breast, lung, prostate and colon cancer primarily via repression of Src suggesting that repression of PAG1 may also be an important event in NB pathogenesis." (PMID 26993602, 2016).
Diabetes (2 papers, 2021 to 2024). "Genes such as KCNE2, DLL1, ACVR1C, RGS3, MLXIPL (MLX interacting protein like), PAG1, SLC2A10 and GRB14 play important role in type 2 diabetes mellitus progression." (PMID 33902539, 2021).
laryngeal carcinoma (2 papers, 2017 to 2023). Carcinoma that arises from the laryngeal epithelium. "Furthermore, the PAG1 gene has also been identified as a promising novel radiosensitization target for laryngeal carcinoma." (PMID 27823965, 2017).
latent infection (2 papers, 2017 to 2018). "During latent infection, several microRNAs (miRNAs) are produced from persistency-associated gene 1 (pag1) as the only detectable HzNV-1 transcript." (PMID 30546025, 2018). "Similar to the LAT gene of HSV, pag1 plays an important role during HzNV-1 latent infection." (PMID 30546025, 2018).
neuroblastoma (2 papers, 2016 to 2023). Neuroblastoma (NB) is the most common solid, extracranial childhood tumor. "This is consistent with previous work showing that FYN and LYN show different responses in activity, association with the scaffold protein PAG1, and intracellular localization when activated by different RTKs in neuroblastoma cells." (PMID 36996232, 2023).
abortion (1 paper, 2024). the ending of pregnancy by removing a fetus or embryo before it can survive outside the uterus. "This study aimed to investigate the impact of ambient lead (Pb) exposure on progesterone (P4) and pregnancy-associated glycoprotein 1 (PAG1) and their relationship with abortion in Egyptian Zaraibi goats (C. hircus)." (PMID 38214824, 2024). "The regression and correlation analyses were performed to determine the significant relationships and correlation coefficients of ambient Pb ions with gestation stages and serum PAG1 and P4 levels to clarify their effect on abortion." (PMID 38214824, 2024). "This means that the serum Pb level of ≥ 32.08 μg/dl will cause abortion, but below this value will not, and vice versa for P4 and PAG1 ≤ 0.48 ng/ml and ≤ 0.95 ng/ml will induce abortion." (PMID 38214824, 2024).
Allergy (1 paper, 2025). An allergy is an immune response or reaction to substances that are usually not harmful. "Proteins such as LRRFIP1, involved in monocyte activation and lysosomal function, and PAG1, linked to allergy development, were prominently recognized." (PMID 41303346, 2025).
chronic kidney disease (1 paper, 2023). Impairment of the renal function secondary to chronic kidney damage persisting for three or more months. "In this study, we investigated the potential of EGF, ZFP36, and PAG1 as biomarkers for chronic kidney disease (CKD)." (PMID 37988198, 2023).
clear cell renal cell carcinoma (1 paper, 2015). "PAG1 attracted our attention because it had been reported to be overexpressed in clear cell renal cell carcinoma (ccRCC) which is frequently associated with loss of VHL function and constitutive HIF-2α overexpression." (PMID 26007655, 2015).
diabetic nephropathy (1 paper, 2023). "Bioinformatics and experimental validation have thus identified EGF and PAG1 as necroptosis-related biomarkers for diabetic nephropathy." (PMID 37988198, 2023). "Three necroptosis-related biomarkers, EGF, PAG1, and ZFP36, were identified and showed strong diagnostic ability for diabetic kidney disease." (PMID 37988198, 2023). "Therefore, we focused on the role of necroptosis in diabetic nephropathy (DN) and identified EGF, PAG1, and ZFP36 as potential biomarkers associated with necroptosis using the WGCNA algorithm." (PMID 37988198, 2023).
glioblastoma (1 paper, 2020). The most malignant astrocytic tumor (WHO grade IV). "Additionally, knockout of PAG1 or ZNF830 in GSCs delayed the onset of neurological signs in orthotopic glioblastoma xenografts compared to GSCs treated with a non-targeting sgRNA." (PMID 32499560, 2020).
glomerulopathies (1 paper, 2015). "These gene array data were validated by RT-qPCR in an independent patient cohort, supporting the association of induced PAG1 levels and several advanced glomerulopathies." (PMID 26007655, 2015).
leukemia (1 paper, 2015). A malignant (clonal) hematologic disorder, involving hematopoietic stem cells and characterized by the presence of primitive or atypical myeloid or lymphoid cells in the bone marrow and the blood. "Different patterns of PAG1 and PTPN11 phosphorylation in leukemia and prostate cancer are associated with different activation states of SFKs and other signaling effectors." (PMID 25884760, 2015).
lymphoma (1 paper, 2025). A malignant (clonal) proliferation of B- lymphocytes or T- lymphocytes which involves the lymph nodes, bone marrow and/or extranodal sites. "PAG1 demonstrates elevated expression profiles across multiple lymphoma subtypes and renal cell carcinomas." (PMID 40282426, 2025).
viral infections (1 paper, 2018). "Nevertheless, the exact mechanism by which pag1 alters viral infections remains unknown." (PMID 30546025, 2018).
tumor (12 papers, 2013 to 2025). "For each tumor sample, a prognostic risk score was computed employing the equation below: prognostic risk score = PAG1 expression × 0.2399877 + LHFPL2 expression × 0.2969381 + FABP5 expression × 0.2441960 (TCGA)." (PMID 37589508, 2023). "The putative tumor suppressor gene PAG1 encodes a transmembrane adaptor protein that binds to the tyrosine kinase Csk and participates in the negative control of T cell receptor (TCR) signaling." (PMID 32603365, 2020). "Another E14-type temporal-axis gene, Pag1 (Cbp), encodes a transmembrane adaptor protein that functions as a suppressor of Src-mediated tumour progression by promoting the inactivation of Src39." (PMID 27094546, 2016). "Other disease factors, such as relapse or tumor progression, and risk of death due to disease was also found to inversely correlate with PAG1 expression (p<0.001)." (PMID 26993602, 2016). "Here, we present in vitro, in vivo, and clinical data defining the major repressor of c-Src, PAG1 (Phosphoprotein Associated with Glycosphingolipid-enriched microdomains 1), as a novel tumor suppressor in high-risk NB." (PMID 26993602, 2016). "These in vivo studies further validate our in vitro observations that PAG1 is able to serve as a potent tumor suppressor in NB." (PMID 26993602, 2016). "We further verified the expression levels of PAG1 in harvested tumor tissues, and as expected, observed increased PAG1 expression in PAG1-OEX xenograft tumor tissues compared to parental control cell line tumors." (PMID 26993602, 2016). "It is worth noting that among the genes in Set A whose expression is down-regulated abound those with tumor-inhibitory activity (e.g., Pag1, PadI4, Lats2, and Cxcl3), while among the up-regulated genes are present tumor facilitators (e.g., Rab18, Dek)." (PMID 27965576, 2016). "Here we demonstrate that increased expression of PAG1 decreases c-Src activation and inhibits tumor growth in vivo, and this correlates with reduced levels of pAKT and pERK." (PMID 26993602, 2016). "Our results establish PAG1 as a potent tumor suppressor in NB by inhibiting c-Src and downstream effector pathways." (PMID 26993602, 2016). "In order to define the mechanism(s) of action for PAG1 as a tumor suppressor, we performed Western blot analysis for c-SRC and associated downstream signaling pathways." (PMID 26993602, 2016). "In summary, we demonstrate that PAG1 significantly alters NB tumor proliferation and xenograft formation." (PMID 26993602, 2016). "Results show that both NGP and SH-SY5Y PAG1-OEX cell line cohorts have significant (p<0.01) reduction in tumor weights in contrast to parental control cell line and PAG1-KD cell line xenograft cohorts." (PMID 26993602, 2016). "Overall, our findings demonstrate potent tumor suppressor functions for PAG1 and suggest transcriptional repression of PAG1 is a major mechanism for c-Src hyperactivity in NB." (PMID 26993602, 2016). "However, PAG1 can be considered an oncogene or a tumor suppressor gene, depending on tumor type, and its expression is not homogeneous across the different types of cancers." (PMID 34141616, 2021). "The elucidation of the pathway(s) that lead to tumor suppressor PAG1 down-regulation may shed light on the mechanisms of NB tumor progression, and pave the way for developing new therapeutic interventions for children suffering with this deadly malignancy." (PMID 26993602, 2016). "Upregulated EOMES and TNFSFR9 and downregulated genes (PAG1, GNLY, ANXA1, FGFBP2) that are involved in tumor escape from immune surveillance by suppressing T-cells or by reprogramming T-cells toward T-cell exhaustion." (PMID 40079005, 2025). "In contrary we found upregulated (EOMES, TNFSFR9, TIGIT, KLRD1) and downregulated genes (PAG1, GNLY, ANXA1, FGFBP2) that are involved in tumor escape from immune surveillance by suppressing T-cells or by reprogramming T-cells toward T-cell exhaustion." (PMID 40079005, 2025).
tumor (continued). "Furthermore, overexpression of miR-143-3p may also enhance anti-tumor effects by targeting ABL2 and PAG1." (PMID 40282426, 2025).
cancer (6 papers, 2015 to 2025). A tumor composed of atypical neoplastic, often pleomorphic cells that invade other tissues. "PAG1 is also reported to be controlled at epigenetic level in cancer cells, and treatment with a histone deacetylase (HDAC) inhibitor as well as by siRNA against HDAC1/2 restore PAG1 expression and activity." (PMID 26993602, 2016). "mRNA levels of both PAG1 and the well-known hypoxia-inducible CAIX were robustly upregulated by 3- to 11-fold in all cancer cell lines examined, except in VHL-deficient 786–0 ccRCC in which PAG1 levels were constitutively high." (PMID 26007655, 2015). "We first confirmed hypoxic PAG1 induction in a panel of cancer cell lines derived from a broad range of different tissues." (PMID 26007655, 2015). "In addition to influencing T cell differentiation, ABL2 and PAG1 have been identified as potential therapeutic targets in cancer." (PMID 40282426, 2025). "Thus accumulating evidence suggests that transcriptional regulation of PAG1 plays an important role regulating SFKs in cancer via multiple interactions." (PMID 26993602, 2016).
infection (2 papers, 2014 to 2018). The state of being infected such as from the introduction of a foreign agent such as serum, vaccine, antigenic substance or organism. "Because pag1 is a noncoding transcript, it potentially regulates host chromatin structure through miRNAs upon infection." (PMID 30546025, 2018). "Two miRNAs (miR-795 and miR-475) were expressed in untransfected cells, and there was no clear increase in their expression level upon pag1 infection, suggesting that insect cells normally express low levels of these two miRNAs and they were not likely derived from pag1 transcript." (PMID 30546025, 2018).
PAG1 also shares sentences with these, for which no sentence is quoted: glioma (2 papers); acute lung injury (1); acute myeloid leukemia (1); anemia (1); Arthritis (1); Cardiomyopathies (1); Cardiovascular Diseases (1); colorectal neoplasm (1); COVID-19 (1); heart failure (1); Hypertensive disease (1); injury (1); interstitial lung disease (1); kidney disease (1); Liver carcinoma (1); liver cirrhosis (1); melanoma (1); Obesity (1); osteoporosis (1); ovarian carcinoma (1); prostate carcinoma (1); psoriasis (1); pulmonary fibrosis (1); renal cell carcinoma (1); rheumatoid arthritis (1); stomach carcinoma (1); T-cell lymphoma (1); type 2 diabetes mellitus (1); uveal melanoma (1).